IL17A (interleukin 17A)
Diseases named in the same sentence as IL17A in open-access papers (continued):
Sharing a sentence is not in itself a finding about the gene and the disease.
ischemic stroke (continued). "Several studies have suggested that Th17 cells and IL-17+ γδ T cells were two major sources of IL-17A after ischemic stroke." (PMID 35663549, 2022). "In the present study, we identified IL-17A induction in γδ T cells as an additional mechanism for IL-1-mediated neutrophil recruitment in ischemic stroke." (PMID 35384588, 2022). "It has been reported that these two groups of cells are the main source of IL-17A after ischemic stroke." (PMID 35663549, 2022). "Our previous research indicated that IL-17A production increased both in the CSF and serum of ischemic-stroke mice that contributed to ischemic injury." (PMID 33101005, 2020). "Evidences also indicated that the expression of IL-17A increased both in the brains of mice and humans after ischemic stroke and was one of the most important inflammatory cytokines." (PMID 33101005, 2020). "Among the inflammatory cytokines, IL-17A was reported to aggravate secondary tissue damage after ischemic stroke." (PMID 33101005, 2020). "A recent study demonstrates a marked decrease of peripheral Treg and a dramatic increment of Th17 cells, accompanied by the increase of IL-17A and RORγt expression, in patients at 1, 5 and 10 days after ischemic stroke." (PMID 31803028, 2019). "In an ischemic stroke model, IL-17A-producing γδ T cells were thought to enlarge infarct size, and both IL-17A and its receptor are increased after ischemic brain injury." (PMID 31803028, 2019). "In this study, we explored the exact role and molecular mechanism of IL-17A in neuronal autophagy after ischemic stroke both in vivo and in vitro." (PMID 31921197, 2019). "Gamma-delta T cells, which are with Th17 the main producers of IL-17A, increase dramatically during ischemic stroke." (PMID 28373915, 2017). "In animal models, reducing neutrophil invasion through IL-17A-blocking antibody has been shown to decreased infarct size and improved neurologic outcome in ischemic stroke and has been shown to improve survival in endotoxic shock." (PMID 25349536, 2014). "We aimed to determine γδT cell counts and γδT cell interleukin 17A (IL-17A) production in the clinical setting of ischemic stroke." (PMID 24840735, 2014). "In this study we found that γδT cell numbers were reduced in human ischemic stroke and that γδT cells showed elevated IL-17A secretion." (PMID 24840735, 2014). "More than this, Il-17A also exerted a significant role in ischemic stroke." (PMID 40028265, 2025). "To further verify whether IL-17A/Notch1 signaling is involved in the process of LIPUS promoting the generation of mature OLs in ischemic stroke mice, we added IL-17A monoclonal antibody (IL-17A mAb) to inhibit IL-17A signaling." (PMID 40290135, 2025). "Alternatively, CNS-derived IL-17A could originate from astrocytes, supported by prior observations of substantial IL-17A/astrocyte co-localization in murine ischemic stroke models." (PMID 40867579, 2025). "IL-17A promotes neurodegeneration and neuroinflammatory responses in MS and ischemic stroke." (PMID 40290135, 2025). "Noteworthy, IL-17a plays a dual role at different time points after ischemic stroke in mice." (PMID 35432162, 2022). "These stimulatory effects of both IL-1 and IL-23 on IL-17A production were already demonstrated in vitro, and our data clearly suggest that both pathways participate in γδ T cell activation following ischemic stroke in vivo." (PMID 35384588, 2022). "The corner and wire hanging test results indicated that IL-17A-neutralizing mAb could improve the motor function compared with that of IgG isotype-treated mice with ischemic stroke (p < 0.001, n = 6 per group)." (PMID 33101005, 2020). "However, which cell apoptosis pathways that triggered by IL-17A is unclear during the development of ischemic stroke." (PMID 33101005, 2020).
ischemic stroke (continued). "Our previous results also demonstrated that IL-17A levels in peri-infarct cortex homogenates, CSF and serum were significantly increased in mice with ischemic stroke; and the blockade of IL-17A with neutralizing antibody improved the neurologic outcome of mice after ischemic stroke." (PMID 31921197, 2019). "γδT cells in human ischemic stroke are reduced in number and show elevated levels of IL-17A." (PMID 24840735, 2014). "Consistent with prior observations, we further demonstrated that IL-17A-mediated excessive autophagy aggravated neuronal ischemic injuries via Src-PP2B-mTOR pathway, and IL-17A neutralization could improve the neurological outcomes of mice with ischemic stroke." (PMID 31921197, 2019). "Moreover, IL-17A neutralization could improve the neurological outcomes of mice with ischemic stroke, which may provide a potential therapeutic effect for ischemic stroke in clinic." (PMID 31921197, 2019). "However, the role of autophagy and IL-17A in ischemic stroke are still ambiguous." (PMID 31921197, 2019). "Thus, OGD/R treatment with the presence of IL-17A was employed to simulate in vivo ischemic stroke." (PMID 31921197, 2019). "In addition, the injection of IL-17A neutralizing monoclonal antibody (mAb) could reduce the infarct volume and improve neurological outcome of mice with ischemic stroke." (PMID 31921197, 2019). "Within 24 hours after the onset of ischemic stroke, specific γδ T cell subsets (Vγ6+CCR6+ and Vγ9+Vδ2+), upon binding to IL-17R, release IL-17A and become the primary source of IL-17A." (PMID 40746532, 2025). "Th17 cells and IL-17A exacerbate blood-brain barrier (BBB) damage, promote infiltration of peripheral immune cells, and increase neuronal injury following ischemic stroke." (PMID 40948793, 2025). "Experimental works suggest a negative impact of γδT cells on the course and prognosis of ischemic stroke, which could be caused by the synthesis of pro-inflammatory IL-17A promoted by γδT cells, which stimulates the recruitment of neutrophils and their migration to the ischemic zone." (PMID 39195289, 2024). "Taken together, IL-17A, TNF-α, and VEGF-A are closely related to ischemic stroke occurrence and development." (PMID 37287803, 2023). "Astrocytes attracted neutrophils in ischemic stroke by increasing the secretion of CXCL1 in response to the synergistic effects of TNF-α and IL-17A." (PMID 34248961, 2021). "In this study, we found that the intracerebroventricular injection of IL-17A-neutralizing monoclonal antibody (mAb; 2.0 μg) could reduce the infarct volume, alleviate neuron loss, and improve the neurological outcomes of mice with 1-h MCAO/R 24-h- or 3-day-induced ischemic-stroke mice." (PMID 33101005, 2020). "In addition, the injection of IL-17A-neutralizing mAb could significantly increase Bcl-2 expression levels (p = 0.0414, n = 6 per group), but decrease the expression levels of Bax (p < 0.01, n = 6 per group) in the peri-infarct region of mice with ischemic stroke." (PMID 33101005, 2020). "In order to elucidate factors that affect the clinical course of ischemic stroke, IL-6 and IL-17A levels were analyzed in patients not complicated with infection (non-SAI)." (PMID 23936327, 2013). "We previously reported that the levels of astrocyte-derived interleukin-17A (IL-17A) increased both in the peri-infarct region and cerebrospinal fluid (CSF) of mice with 1-h middle cerebral artery (MCA) occlusion/12-h reperfusion (1-h MCAO/R 12 h)-induced ischemic stroke." (PMID 33101005, 2020). "However, in another study, IL-17A could maintain and augment survival and neuronal differentiation of NPCs in the subventricular zone (SVZ) after ischemic stroke." (PMID 32317974, 2020). "However, IL-17A was also found to maintain and augment the survival and neuronal differentiation of NPCs in the SVZ and subsequently influence synaptogenesis and spontaneous recovery after ischemic stroke." (PMID 32317974, 2020).
leishmaniasis (69 papers, 2010 to 2026). Infectious disease that is transmitted through the bite of hematophagous female phlebotomine sand flies. "Regarding leishmaniasis, conflicting mouse and human studies associate IL-17A with both protection and pathology." (PMID 37764937, 2023). "The destructive potential of IL-17A in leishmaniasis has also been corroborated in human disease, where IL-17A-mediated cell infiltration was linked with tissue damage in human mucosal leishmaniasis caused by L. braziliensis parasites." (PMID 27658195, 2016). "TNF, IFN-γ, and IL-17A have been strongly associated with protection during leishmaniasis." (PMID 36189274, 2022). "Still, our data demonstrated an overall increased expression of inflammasome-related genes such as Gsdmd, Nlrp3, Casp1, Casp4, Il1b, Ifng, Tnfa, Il10, and Il17a when we compared Leishmaniasis patients with controls." (PMID 36828815, 2023). "We recently reported that patients, suffering from chronic forms of leishmaniasis caused by Lgy had decreased levels of IFN-γ and high levels of the inflammatory cytokine IL-17A." (PMID 36034693, 2022). "IL-17A is the founding member of this family, together with IL-17B, C, D, E and F, and the most well-studied in leishmaniasis." (PMID 33415318, 2020). "In experimental models of leishmaniasis, the roles of IL-17A and IL-27 are still controversial: IL-17A, in synergy with IFN-γ, has been shown to potentiate leishmanicidal activities of infected macrophages." (PMID 27965662, 2016). "The relationship between IL-17A and protection against leishmaniasis in SOT recipients deserves further study." (PMID 26496365, 2015). "Taken together, these results indicate that the detection of LRV1 or IL-17A in leishmaniasis has significant prognostic value and could be used to guide the therapeutic approach for the prevention and treatment of metastatic leishmaniasis." (PMID 27658195, 2016). "Further, as IL-17A has been shown to be pathologic in other forms of leishmaniasis, these drugs may hold therapeutic potential across a broader range of leishmanial species." (PMID 27658195, 2016). "While IL-17A neutralizing antibodies are available, this is not an economically feasible treatment option for the vast majority of leishmaniasis patients." (PMID 27658195, 2016). "Similarly, by treating our C57BL/6 murine model of leishmaniasis with digoxin and SR1001, we were able to significantly decrease IL-17A production in draining LNs resulting in a reduction of disease severity that reached levels comparable to that of the IL-17A-/- model." (PMID 27658195, 2016).
sarcoidosis (69 papers, 2010 to 2025). Sarcoidosis is a multisystemic disorder of unknown cause characterized by the formation of immune granulomas in involved organs. "Additionally, Th17 cells produce the potent proinflammatory cytokine IL-17A, which plays a crucial role in sarcoidosis-associated inflammation." (PMID 26845566, 2016). "The behaviour of Th17 cells in peripheral blood can be complex, as some studies indicate that memory CCR6+ T cells are more abundant in sarcoidosis groups, whereas in some studies IL-17A-producing cells numbers are low in peripheral blood." (PMID 41376646, 2025). "In various chronic, autoimmune, inflammatory diseases, such as sarcoidosis, the percentage of IL-17A+/IFN-γ+ double-producing Th-cells increases in peripheral blood and is related to high disease activity." (PMID 37868478, 2023). "An increased expression of interleukin 17A (IL-17A) has been described in patients with sarcoidosis, and IL-17A-positive CD4+ T cells have also been shown to infiltrate sarcoid lung lesions from patients at different stages of disease evolution." (PMID 34440765, 2021). "A few studies have analyzed the roles of the Th17 effector cytokines IL-17A/F, IL-21, and IL-22 in the pathogenesis of sarcoidosis." (PMID 26845566, 2016). "A few studies have analyzed the role of the Th17 effector cytokines IL-17A/F, IL-21, and IL-22 in sarcoidosis, but the results are contradictory." (PMID 25386143, 2014). "IL-17A+ cells are also suggested to be highly present in patients showing relapses of sarcoidosis." (PMID 40724901, 2025). "IL-17A+ cells are also suggested to be persistently present in patients affected by sarcoidosis." (PMID 40724901, 2025). "Elevation of IL-17A levels has been found in patients with sarcoidosis." (PMID 31474992, 2019). "Recently, newly identified Th17.1-cells in sarcoidosis and IL-17A, which has a specific role in the lungs, prompt new questions for their functional role as may be implicated in separate immune molecular mechanisms in LS and non-LS sarcoidosis." (PMID 31819081, 2019). "IL-17A may play an important pro-inflammatory role in the development of sarcoidosis-like granulomatosis." (PMID 31474992, 2019). "Furthermore, we found a negative correlation between BALF CD4+ T cell IL-17A expression and BALF CD4/CD8 ratio in sarcoidosis, suggesting that the alveolitis seen in patients is associated with an influx of CD4 T cells with on average merely little production of IL-17." (PMID 20813038, 2010). "Although IL-17A plays a key role in protecting mucosal surfaces, excessive or uncontrolled IL-17A activity promotes chronic inflammation in both EAT and C. acnes-induced sarcoidosis models." (PMID 40837573, 2025). "Active sarcoidosis is characterized by an enhanced local expression of T helper 1 (Th1) and T helper 17 (Th17) chemokines and cytokines like IFN-γ, TNF-α, IL-17A, and IL-22." (PMID 37868478, 2023). "We noted similarly increased mRNA and protein expression of the master transcription factor regulating IL-17A production, RORC, in CD4+ T cells from the male compared to the female sarcoidosis patients." (PMID 36899902, 2023). "An analysis of female sarcoidosis patients revealed a significant reduction in pSTAT3 and IL-17A levels and a concomitant increase in TGF-β1 levels in CD4+ T cells compared to male sarcoidosis patients." (PMID 36899902, 2023). "We observed higher IL-17A mRNA and protein expression in CD4+ T cells from male compared to female sarcoidosis patients." (PMID 36899902, 2023). "Levels of Th17 (IL17-A, IL17-F) and Th2 (IL-4, IL-13) cytokines tended to be less abundant in sarcoidosis patients relative to controls." (PMID 35668129, 2022). "Vitreous levels of IL-4, IL-17A, IL-22, IL-31, and TNFα in PDR patients were also significantly higher than those of sarcoidosis patients." (PMID 26352837, 2015).
sarcoidosis (continued). "Researchers have found that IL-17A-expressing CD4+ T lymphocytes or IL-17A+IFN-γ+ memory T cells and RORγt, a nuclear receptor crucial for the differentiation of Th17 cells, are increased in both the BAL and the peripheral blood of patients with sarcoidosis." (PMID 40724901, 2025). "Moreover, recent studies have suggested an important role of IL-17 in sarcoidosis, and enhanced expression of IL-17A+IFN-γ+ and IL-17A+IL-4+ memory T-cells was shown in sarcoidal lungs." (PMID 32823524, 2020). "Since there are to date no murine models of sarcoidosis it is difficult to verify whether Th17/IL-17A contribution is essential in sarcoidosis as well." (PMID 25386143, 2014). "Thus, while the detection of TH17 or TH17.1 cells themselves cannot be used as specific markers of sarcoidosis outcome, the presence of TH17/TH17.1 cells along with elevated levels of TGF-β1, IFN-γ, or IL-17A may prove to be a valuable indicator of disease severity and progression." (PMID 33036432, 2020). "Recent studies have found a predominant increase of IL-17A+CD4+ memory T cells in the peripheral blood and bronchoalveolar lavages of pulmonary sarcoidosis patients, strongly suggesting (Th17) cells may play an important role in the pathogenesis of sarcoidosis." (PMID 24885153, 2014). "However, Löfgren’s syndrome patients differed from non-Löfgren’s syndrome sarcoidosis patients in that their TH1/TH17 cells secreted significantly lower levels of IFN-γ and significantly higher levels of IL-17A." (PMID 33036432, 2020).
Alzheimer disease (67 papers, 2010 to 2025). A progressive, neurodegenerative disease characterized by loss of function and death of nerve cells in several areas of the brain leading to loss of cognitive function such as memory and language. "To summarize, recent evidence highlights the critical role of IL-17A and IL-17A – producing cells in the pathogenesis of Alzheimer's Disease (AD)." (PMID 40469524, 2025). "IL-17A contributes to neuroinflammation in disorders, including Parkinson's disease (PD), Alzheimer's disease (AD) and amyotrophic lateral sclerosis." (PMID 37680650, 2023). "Clinically, it was found that the levels of IL-17A in the plasma and cerebrospinal fluid of Alzheimer’s disease patients were elevated." (PMID 35392087, 2022). "Levels of some cytokines (IL-15 and IL-17A) were highest in brains from Alzheimer’s disease patients with BSV–VI disease." (PMID 33723589, 2021). "According to this, blocking of IL-17A in a wild-type mouse model of lung Ad resulted in a decreased number of Foxp3+ Tregs and an increase of IFN-γ and TNF-α producing CD4+ T cells leading to a significant reduction of tumor growth." (PMID 22855687, 2012). "Multiple brain cytokines were elevated in Alzheimer’s disease and vascular dementia: IL-15 and IL-17A were maximally elevated in end-stage Alzheimer’s disease (Braak tangle stage V–VI) whereas IL-2, IL-5, IL12p40 and IL-16 were highest in intermediate Braak tangle stage III–IV disease." (PMID 33723589, 2021). "Moreover, blocking of IL-17A in a mouse model of lung Ad resulted in a decrease of Foxp3+ Treg numbers." (PMID 22855687, 2012). "An interaction effect was observed between Alzheimer’s disease status and systemic infection indicating that GM-CSF, IL-17A, IFN-γ, and IL-12 were significantly altered by infection in Alzheimer’s disease." (PMID 33723589, 2021). "Old mice underwent hepatectomy surgery in the presence or absence of IL17A monoclonal antibody, and cognitive function, hippocampal neuroinflammation, and pathologic markers of Alzheimer’s disease (AD) were assessed." (PMID 26509545, 2015). "The cytokine interleukin-17A (IL-17) is involved in the learning and memory process in the central nervous system, and its level was reported to be increased in Alzheimer's disease (AD) brains, while the effect of IL-17 on the course of Aβ has not been well defined." (PMID 36823558, 2023). "The presence of IL-17A in mast cells in the spinal cord of patients with ALS and Alzheimer disease has not been previously reported." (PMID 21062492, 2010).